IL4 (interleukin 4)
Diseases named in the same sentence as IL4 in open-access papers (continued):
Sharing a sentence is not in itself a finding about the gene and the disease.
tumor (continued). "Signaling via the Hippo pathway, including its effectors YAP/TAZ, drives the expression/secretion of numerous cytokines (e.g., IL-4, IL-6, CSF-1) that help recruit monocytes to the TME, followed by their M2-like polarization into TAMs that express tumor immune checkpoints such as PD-1." (PMID 39410029, 2024). "Conversely, by producing IL-4, -5, and -13, Th2-polarized CD4+ T cells may be involved in the downregulation of T cell-mediated cytotoxicity and in the induction of a tumor-promoting response." (PMID 38891095, 2024). "However, the expression of molecules such as interleukin-4 (IL-4), colony-stimulating factor 1 (CSF-1) and arginnse-1 (Arg-1) in the TME are increased with the development of tumor, which induce the transformation of M1-type TAMs into M2-type TAMs." (PMID 38970071, 2024). "Moreover, the expression of ADAM10 was reciprocally exclusive with some tumor immune checkpoint genes, such as VEGFB, LAG3, IL4, TNFRSF18, TNFRSF4, TNF receptor superfamily member 14 (TNFRSF14), CD27, CCL5, etc.." (PMID 39211038, 2024). "The DMPtNPS@cGAMP + RT group exhibited a significant increase in anti‐tumor cytokines, namely IFN‐γ, IFN‐α, IFN‐β, TNF‐α, and IL‐2, and a more pronounced decrease in pro‐tumor cytokines, including IL‐1β, IL‐10, IL‐4, and TGF‐β, as measured by ELISA kits, in comparison to the other treatment groups." (PMID 38063844, 2024). "Tregs are a subgroup of inhibitory T cells that play an immunosuppressive role following activation in the body via the secretion of IL-4, IL-10, and TGF-β and participate in the immune escape mechanism of tumours, promoting the occurrence and development of tumours." (PMID 38475858, 2024). "Interleukin-4 (IL-4): IL-4 is an immunoregulatory cytokine that can contribute to immunosuppression in TNBC by promoting the polarization of macrophages toward the M2-like phenotype, which supports tumor growth and inhibits immune responses." (PMID 38397971, 2024). "Both TGF-ß and IL-4 are known to antagonize MHC class II expression and might contribute to rendering the tumor cells less immunogenic." (PMID 38500877, 2024). "M2 macrophages—“bad macrophages,” induced by Th2 cytokines (e.g., IL-4, IL-10, IL-13), produce anti-inflammatory cytokines (e.g., IL-10, IL-13, TGF-β) promoting tumor growth, ECM remodeling to facilitate tumor invasion, metastasis, angiogenesis, and immune suppression." (PMID 39201585, 2024). "MEG3 also inhibited IL4/13 stimulated M2 polarisation as upregulation of MEG3 expression in M2-Bone Marrow-Derived Macrophages (M2-BMDMs) downregulated M2 markers like CD206, YM1, MRC and ARG1, ameliorating tumour proliferation in macrophage-Huh7 co-culture." (PMID 40176927, 2024). "Furthermore, tumor cells create an immunosuppressive environment by augmenting the secretion of anti-inflammatory cytokines, such as TGF-ß and IL-4, while reducing the secretion of pro-inflammatory cytokines, such as IL-15 and IFN-γ." (PMID 38500877, 2024). "These pathways may also indirectly regulate IL-4, IL-9, and TNF-α, as these cytokines frequently interact with metabolic and proliferative pathways within the tumor microenvironment." (PMID 39727942, 2024). "After 16 days, tumor tissue was processed, and an increase in M1 markers and a decrease in M2 markers, as well as an increment in pro-inflammatory cytokines such as TNF-α and a reduction in immune-suppressing cytokines IL-4, IL-10 and TGF-β, were measured." (PMID 39061247, 2024). "Scholars have stated that kefir reduces tumor cell viability and growth rates, regulates cytokine expression in tumor tissues (e.g., downregulates IL-6, IL-10 and IL-1β, upregulates TNF-α, IL-10, and IL-4), promotes apoptosis, and exerts immune-enhancing effects." (PMID 39605907, 2024).
tumor (continued). "M2-type macrophages primarily secrete anti-inflammatory cytokines like interleukin 10 (CXCL-10), interleukin 13 (IL-13), and interleukin 4 (IL-4), and express abundant arginine-1, mannose receptor (MR, CD206), and scavenger receptor, which contribute to tumor growth and spread." (PMID 38655133, 2024). "Chemotherapy drugs can enhance the recognition and presentation of dendritic cells (DCs), activate cytotoxic T lymphocytes to attack tumors, stimulate the release of interleukin-2 (IL-2), IL-4, and interferon-gamma (IFN-γ), and induce anti-tumor immune responses." (PMID 38809459, 2024). "In contrast, TA-specific interleukin (IL)-4-producing CD4+ T helper (Th2) cells evolved as a negative prognostic marker within the tumor microenvironment (TME) as they promote tumor growth by enhancing angiogenesis and inhibiting cell-mediated immunity 24-26." (PMID 39239511, 2024). "Moreover, puerarin decreases the level of pro-tumor cytokines (IL-10, TGF-β, and IL-4) and increases the expression of anti-tumor cytokines (IFN-γ, IL-12, and TNF-α)." (PMID 38361933, 2024). "IL-4 and IL-13, which are involved in Th2-type immune responses, are among the major stimuli that induce TAM tendency toward the M2 phenotype that promotes abnormal tumor angiogenesis and tumor progression." (PMID 39403370, 2024). "With tumor cell stimulation, the CART-19 cells exhibited heightened functional cytokine and chemokine secretion, especially the production of GM-CSF, IFN-γ, IL-2, IL-4, IL-8, IL-12, IL-13, MIP-1α/β, and TNF-α/β." (PMID 38773607, 2024). "By combining a first-generation anti-PSCA CAR with two hybrid cytokine receptors to convert immunosuppressive transforming growth factor beta (TGFβ) and interleukin 4 (IL4) cytokine signaling into co-stimulatory signaling, maximal CAR-T cell activity was restricted to the tumor site." (PMID 39095991, 2024). "(f) An intron variant in STAT6 (Signal Transducer And Activator Of Transcription 6), which transduces IL4 and IL13-mediated signaling, regulates the expression of genes involved in the immune response, cell survival, and tumor proliferation and metastasis, hence, it has oncogenic functions in CRC15." (PMID 39715885, 2024). "Upregulation of IL-4/IL-4R signaling in TAMs results in their increased secretion of insulin-like growth factor (IGF-1), which, upon binding to IGF-1 receptor (IGF-1R) on tumor cells, upregulates the PI3K pathway, promoting tumor growth and malignancy." (PMID 38254796, 2024). "CCT3-mediated Th2 deviation in tumor microenvironment may link to a worse outcome for LUAD, since Th2 cytokines IL-4 IL-5, IL-9 and IL-13 trigger the differentiation of tumor-associated M2 macrophages." (PMID 36918801, 2023). "Th2 cells always give rise to a humoral immune response that promotes tumor growth through the secretion of IL-10, IL-4, and TGF-β; by contrast, Th1 cells can secrete IFN-γ, TNF-α, and IL-12 to mediate the anti-tumor response and provide successful protection against cancer." (PMID 37345110, 2023). "Decreased tumor weight.Increased secretion of TNF-α, IFN-γ, and IL-2.Decreased secretion of IL-4." (PMID 38136228, 2023). "However, Th2 cells are considered to promote tumor progression due to the immunosuppressive substances they release, including TGF-β, IL-4, IL-5, and IL-13." (PMID 38203661, 2023). "Tumor-associated macrophages (TAMs) derive from circulating monocytic precursors, infiltrating macrophages in tumor tissue are driven by tumor-derived cytokines (e.g. IL-10, TGF-β) and T cell-derived cytokines (e.g. IL-4, IL-13) and acquire a polarized M2 phenotype." (PMID 37691932, 2023). "The results showed that GA significantly enhanced the anti-tumor effects, cytokine production as well as the expansion of anti-CD19 CAR-T cells, which may be mainly through the activation of IL4/JAK3-STAT3 signaling pathway." (PMID 36871129, 2023).
tumor (continued). "Previous research also demonstrated that Th2 cells could secrete IL‐4 and IL‐5 contributing to antitumor response by regulating TME and recruiting other effector cells in the tumor model with vaccination." (PMID 37829505, 2023). "IL-4 activated M2 macrophages by c-Jun N-terminal kinase-signal transducer and activator of transcription (JNK-STAT) pathway and impaired DC functions, indicating that higher expression of UVRAG in epithelial cells was correlated with tumor immune escape." (PMID 37173968, 2023). "CD3/CD28 stimulated lymph node cells produced slightly higher but not significant levels of IL-4 in tumor-bearing compared to non-tumor-bearing mice in both LY2 and MOC2 HNSCC models." (PMID 37444444, 2023). "Evaluation of cytokine changes in the tumor microenvironment by ELISA-based analysis of tumor lysates demonstrated that combined blockade elevated the levels of cytokines IFN-γ, TNF-α, IL4, M-CSF, GM-CSF, and CCL2, while it suppressed the immune suppressive cytokine TGF-β." (PMID 37449205, 2023). "However, T cells also have pro-tumor activity; CD4+ T cells inhibit CD8+ T cells’ anticancer activity by producing IL-4 and -10, and Th17 cells produce IL-17, which promotes tumor growth." (PMID 37736898, 2023). "In addition, it reduced IL-1β, IL-4, IL-6, IL-10, and IL-13 levels, down-regulated PI3K, ERK1/2, and up-regulated EGFR levels, improving the anti-tumor effects of the tumor suppressor microenvironment." (PMID 37397393, 2023). "While IL-4, IL-6, and IL-10 demonstrated a rise from baseline to tumor response, none of these changes reached statistical significance." (PMID 38022654, 2023). "IL-4 was not analyzed in tumor biopsies and was not used to select subjects for recruitment to this study." (PMID 37321663, 2023). "‐IL‐4‐mediated, STAT6/PI3K‐dependent, macrophage reprogramming, triggered by cholesterol efflux, led to increased arginine metabolism, that promoted immunosuppression and tumor growth." (PMID 36658699, 2023). "Furthermore, IL33 expression levels were positively correlated with those of Th1 cytokines (IL2 and IFNG) and Th2 cytokines (IL4 and IL10) in 41 tumor tissues." (PMID 37056569, 2023). "Similar to our flow cytometry results, lymph node cells from MOC2 tumor-bearing mice did not produce increased IL-4 compared to non-tumor-bearing mice after restimulation with IR MOC2 antigens." (PMID 37444444, 2023). "While several additional markers (e.g., CD63, CD203c) indicated that these tumor-associated basophils were, indeed, activated, relevant mediators commonly released by these cells (histamine, LTC4, IL-4, IL-13) were not investigated." (PMID 37205111, 2023). "This was mediated by a cytokine gradient from non-tumor to tumor tissue involving among others the cytokines IL-33, IL-4 and IL-1β." (PMID 35663967, 2022). "On the other hand, M2 macrophages are part of the Th2 response, are induced by IL-4, produce IL-10 and TGF-β, and are related to an immunosuppressive microenvironment, which favors tumor cell growth, angiogenesis, matrix remodeling, and inhibition of adaptive immunity." (PMID 35055124, 2022). "In line with diminished IL-4 signaling, IL-4ra-KO mice exhibited low expression levels of the alternative macrophage marker genes Arg1 and Il-10, which furthermore, were not enhanced in iWAT in the presence of the cachexigenic LLC tumor." (PMID 35210363, 2022). "The expression of Il4, Il13, Ccl11, Ccl17 and Ccl22 mRNA was increased two- to fourfold, whereas the expression of Tslp mRNA was not changed, in the skin lesions of Ddx5∆KC mice compared with Ddx5fl/fl mice at day 16 post-MC903 administration." (PMID 36271146, 2022). "Analysis of effector cytokines Ifng, Il9, Il17a and Il4 mRNA in tumor-infiltrating immune cells revealed that Ifng and Il9, but not Il17a or Il4, expression was increased following cGAMP administration." (PMID 35091453, 2022).
tumor (continued). "Immunosuppression was observed by eosinophils-derived indoleamine 2,3-dioxygenase (IDO) (inhibition of effector T cells) and by an increasing of IL-4 and IL-13-expression by eosinophils via TSLP leading to conversion of macrophages into tumour-promoting activation state." (PMID 35406451, 2022). "Breg cells-derived IL-10 can have a direct negative impact in T cell anti-tumour responses by disrupting the Th1/Th2 balance and inducing DCs to produce IL-4 and downregulate IL-12 and thus IFN-γ." (PMID 35406451, 2022). "Furthermore, IL-4 and IL-10 restrain IFN-γ production and impair cytotoxic cell-mediated anti-tumor immunity, suggesting that an increased shift from Th1 cells to Th2 cells promotes tumor progression and immunosuppression." (PMID 35646684, 2022). "In contrast to IL4, there was no change in the number of transmigrated tumor cells after pre-stimulation of BMDMs with IL13 (Met-1 cells, n = 3, p-value = 0.33)." (PMID 36077870, 2022). "This response was specific to IL4 signaling, as IL4 stimulation of BMDMs isolated from IL4Rα−/− mice did not enhance tumor cell transendothelial migration (n = 3, p-value > 0.05)." (PMID 36077870, 2022). "As an immunosuppressive microenvironment is favorable for tumor growth and progression, we measured the levels of proinflammatory cytokines (IFN-γ, TNF-α, GM-CSF, and IL-2) and anti-inflammatory cytokines (TGF-β, IL-17, IL-10, and IL-4) within tumors." (PMID 36429032, 2022). "Supporting this hypothesis, the Th2 regulators, Interleukin-4 (IL4) and 13 (IL13), as well as IL10, have been demonstrated to play important roles during primary tumor progression in mouse models of cancer." (PMID 36077870, 2022). "Potential resolutions for these challenges for CAR T cells include targeting multiple tumor antigens, engineered to secrete anti-tumor cytokines, ICI, and inhibitors for immunosuppressive cytokines (TGF-β1 and IL-4), increasing T cell expansion or persistence, and enhancing tumor infiltration." (PMID 36015256, 2022). "Together, these results show that WT BMDMs promote tumor cell transendothelial migration in vitro while IL4Rα signaling from IL4 (but not other Th2 or Th1 cytokines) in macrophages enhances their activity in this process." (PMID 36077870, 2022). "Moreover, Artemisia argyi polysaccharides (FAAP-02) were reported to improve anti-tumor activity by promoting the production of lymphocyte, TNF-α, IL-2, IL-4, IL-6, and IL-12." (PMID 35295918, 2022). "Tumor-promoting cytokines IL-10 and IL-4, though elevated in the 6-hour sample, showed no significant changes during the burst phase." (PMID 35465347, 2022). "The TME expression of IL-4/IL-13, absent from the BM, suggests tumor-specific activation of these powerful pathways that drive both immunosuppression and generation of lymphatic vasculature." (PMID 35442077, 2022). "A previous study has shown that membrane cholesterol efflux drives macrophage IL4‐mediated M2 reprogramming through the PI3K/AKT pathway, and we queried whether engulfment of heat‐treated tumor cells induced membrane cholesterol efflux." (PMID 35037422, 2022). "In addition, the anti-tumor activity of T cells was assessed by measuring IFN-γ, IL-4, and TGF-β levels in the supernatant of T cell/DC co-cultures." (PMID 35979362, 2022). "Notably, SCT treatment slightly decreased CD3+ cell fraction and increased IL‐4+ and IL‐10+ CD4+ T cell populations in the tumor‐infiltrating T cells." (PMID 34747157, 2022). "As IL-10 and IL-4 are known to promote class switching to IgG4, these findings indicate that TNBC may create a tumor microenvironment that supports class switching to the IgG4 subtype." (PMID 35255925, 2022). "The preclinical study showed that these CAR-T cells could not only survive in IL-4-rich TME, but that IL-4 could also boost their activity and anti-tumor ability." (PMID 35392217, 2022).
tumor (continued). "This study showed that IL4 was not required for macrophage enhancement of the transendothelial migration of tumor cells in vitro but did enhance the macrophage’s ability to promote this process." (PMID 36077870, 2022). "Thus, in our following experiments we utilized splenocytes from these two tumor-bearing murine models as initial cells to induce MDSC-DCs with GM-CSF and IL-4." (PMID 35707772, 2022). "Additionally, in vivo studies have also shown that albumin–artemether nanoparticles can control tumor growth by increasing the production of cytokine IFN-γ and decreasing the production of IL4." (PMID 36359230, 2022). "Highly expressed p-STAT3 was positively correlated to high levels of IL-4, IL-6, and IL-10, and negatively correlated to low levels of IFN-γ in the serum, which may contribute to immune surveillance disability against tumor cells." (PMID 35530361, 2022). "In contrast, macrophages treated with TAM or TAM combined with IL-4 had an inhibitory effect on migration, suggesting that TAM inhibited tumor cell migration by abrogating M2 polarization of tumor-associated macrophages and immune checkpoint SHP1/SHP2 blockade." (PMID 35269804, 2022). "However, macrophages undergo polarization and metabolic reprogramming when stimulated by external pathogens, cytokines, and tumor metabolism, such as LPS, IFN-γ, TNF-α, IL-1, IL-4, IL-10." (PMID 35874739, 2022). "Our results showed that T cells in the LUAD tumor microenvironment may communicate with malignant cells at high ATscore levels via PARs, IFN-II and IL-4 pathways, thereby regulating tumor cell proliferation and invasive capacity." (PMID 35529878, 2022). "Moreover, neoadjuvant chemotherapy increased the production of proinflammatory cytokines by tumor-infiltrating T cells, with enhanced TNF-α and IL-2 and reduced IL-4 and IL-10 expression." (PMID 36509285, 2022). "In immune cells, IL-4 and IL-13 can increase polyamine levels that may also contribute to type II NKT cell-mediated tumor immunosuppression." (PMID 36119047, 2022). "IL4 pre-stimulation of Cxcr2−/− BMDMs did not increase transmigration of tumor cells (n = 3, p-value = 0.56), in contrast to the enhanced effect with WT BMDMs (n = 3, p-value < 0.05)." (PMID 36077870, 2022). "Following culture, both splenic and tumor M-MDSCs treated with αIL-4/13Ab-ILC2-SNT had decreased Arg1 expression compared to conAb-ILC2-SNT-treated M-MDSCs, indicating that intestinal ILC2-derived IL-4 and IL-13 can promote Arg1 expression in M-MDSCs." (PMID 35658010, 2022). "Given the association of the pro-tumoral IL-25-ILC2 axis with MDSCs, and the expression of Il4ra and Il13ra1 by M-MDSCs, we sought to investigate whether ILC2-derived IL-4 and IL-13 promote MDSC function to suppress anti-tumor immunity." (PMID 35658010, 2022). "In addition, IL4 induces expression of HGF, which creates an immunosuppressive environment for cytotoxic natural killer cells via c-MET signaling in tumor cells." (PMID 36077870, 2022). "Production of IL-4, IL-6, and IL-8 may induce immunosuppressive myeloid cell differentiation, while CXCL14 affects macrophages recruitment to the tumor." (PMID 36578079, 2022). "Thus, we determined tumor soluble factors that include angiogenic (VEGF), type 1 response (TNF-α, IFN-γ), type 2 response (IL-4, IL-5), and regulatory (IL-10) soluble factors." (PMID 36233245, 2022). "IL-4, IL-6 and IL-10 are abundantly expressed in TME and play more pro-tumor role, while IL-2, IL-12, IL-15 and IL-18, which are immunomodulatory or pro-inflammatory factors, are restricted in the TME and play more anti-tumor role." (PMID 36698392, 2022). "The result was also confirmed on IL-4-stimulated microglial cells: BV2-derived sEVs were not able to modify the expression of pro-tumor genes (Arg-1, Cd163, Cd206, Fizz-1, and Ym1), with all of them upregulated by IL-4 treatment compared to the control cells." (PMID 34440835, 2021).